NOTCH1 (notch receptor 1)
Diseases named in the same sentence as NOTCH1 in open-access papers (continued):
Sharing a sentence is not in itself a finding about the gene and the disease.
breast cancer (continued). "Interestingly, a specimen of breast epithelial hyperplasia also showed cleaved Notch1 and Hes5 positivity, indicating that Notch signaling might be activated at a very early stage of breast cancer progression." (PMID 20030805, 2009). "A recent study showed that WWP2 functions as an E3 ligase for the Notch1 intracellular domain (NICD1) at K1821 and acts as a suppressor of breast cancer metastasis." (PMID 40004017, 2025). "N1ICD/RBPJ was showed to physically interact with ESR1 in breast cancer cells, forming a common complex bound to DNA, which enables ESR1-dependent activation of Notch1-mediated signaling." (PMID 40506655, 2025). "To investigate the contribution of Notch‐1 signalling to collective cell migration in breast cancer, we utilized a stable transfection model with four distinct cell lines (Vector, NICD, Sc.shRNA and Notch‐1 shRNA)." (PMID 39343985, 2025). "We also found novel trans-enhancer hijacking events activating known oncogenes including MYC in the small cell lung cancer cell line NCIH146, NOTCH1 in the T-cell lymphoblastic leukemia cell line CUTLL1, and CCND1 in the breast cancer cell line ZR751." (PMID 39033128, 2024). "MiR-34a inhibited the migration, invasion, and proliferation and modulated drug sensitivity in breast cancer cells by affecting antiapoptotic genes Bcl-2 and CCND1 and the Ras family proteins, NOTCH1 and PRKD1." (PMID 38919953, 2024). "In contrast, downregulation of NOTCH1 decreases HES1 activity, which predicted the inhibition of the bio-functions: migration of tumor cells and invasion of breast cancer cells." (PMID 38337803, 2024). "The Notch-1 pathway plays an important role in tumor development by downregulating the expression of the PTEN in specific types of tumors, such as breast cancer and T-cell leukemia." (PMID 38733531, 2024). "The Notch1 and PI3K/Akt signaling pathways were suppressed in breast cancer stem cells after quercetin treatment." (PMID 38742934, 2024). "Mechanistically, Notch is an inducer of MYC and NOTCH1 and MYC expression positively correlates in breast cancer biopsies." (PMID 38172915, 2024). "ASPH-mediated upregulation of Notch1 signaling by hydroxylation of Notch1 and its ligands has been detected in various cancer types, such as hepatocellular carcinoma (HCC) 8, pancreatic cancer 10, and breast cancer." (PMID 38817852, 2024). "Following chemotherapy for breast cancer, ONECUT2 induces tumor stemness and triggers the expression of stem cell-related genes, including SOX9, SOX2, and NOTCH1, thereby contributing to chemoresistance." (PMID 38997271, 2024). "NRF2 overexpression and KEAP1 knockdown promoted the expression of G6PD and HIF-1α/NOTCH1 to induce EMT and breast cancer migration." (PMID 38424190, 2024). "In the context of breast cancer, FBP1 augments the ubiquitination of Notch1 via the Fbw7 pathway, subsequently leading to its degradation by the proteasome." (PMID 38349431, 2024). "Notch-1 mediates PTEN inhibition, which results in ERK1/2 activation, HER2(+) breast cancer cell proliferation and BCSC survival." (PMID 38505617, 2024). "NOTCH1 and JAG1 are upregulated in breast cancer by KLF4 and BMP4, which, in turn, influences CSC migration and spread." (PMID 39547513, 2024). "NOTCH1 and NOTCH2 downregulation inhibits the proliferation of tumor-initiating cells in several breast cancer cell lines and LUAD cells, respectively." (PMID 38027016, 2023). "In breast cancer, CAF‐derived MFAP5 affects the invasion and migration of tumour cells through the Notch1/slug pathway." (PMID 36855786, 2023). "We earlier demonstrated that ETBF, by virtue of its toxin BFT, enhances breast cancer progression, migration, metastasis, and self-renewal by inducing an EMT response in breast cancer cells via β-catenin and Notch1 pathways." (PMID 37503343, 2023).
breast cancer (continued). "In breast cancer, the HER2+ subtype harbors low Notch1 activity and experimental modeling in mouse and cell lines demonstrated the ability of HER2 to negatively regulate Notch1 activity." (PMID 37440925, 2023). "MYC (FC = 0.75; 95% CI, 0.52-0.99; P < .001) (eFigure 8A-B in Supplement 1) and NOTCH1 (FC = 0.97; 95% CI, 0.81-1.13; P < .001) (eFigure 8C-D in Supplement 1) were also upregulated in TNBC tumors compared with other breast cancer subtypes." (PMID 37796506, 2023). "For example, an anticancer effect accompanied by the downregulation of proteins, such as NOTCH1, Jagged1, DLL4, and HES5, by Resveratrol was observed in MDA-MB-231 breast cancer cells." (PMID 37760535, 2023). "High levels of Notch1, Notch3, JAG1, JAG2, and the target HES-1 are found in pancreatic and breast cancers." (PMID 35205716, 2022). "Nrf-2 activates antioxidant enzymes and upregulates Notch-1 through the G6PD/HIF-1 pathway, thereby affecting the proliferation of breast cancer cells." (PMID 35938165, 2022). "The expression of NOTCH-1, NOTCH-2, and NOTCH-3 was compared in each breast cancer molecular subtype." (PMID 36476410, 2022). "Despite the anti-cancer function in solid tumors like breast cancer and HCC, UBR7 was identified as transcriptional target of NOTCH1 and played an oncogenic role in T cell acute lymphoblastic leukemia." (PMID 36419136, 2022). "However, activated PKCα attenuates Jagged-1-mediated Notch1 activity in ErbB2-positive breast cancer and restores trastuzumab resistance, suggesting that PKCα activity may be a potential prognostic marker for low Notch activity and increased trastuzumab sensitivity in ErbB2-positive breast cancer." (PMID 36358843, 2022). "For example, in breast cancer cells, free EZH2 can directly bind the promoter of NOTCH1 to increase NOTCH1 expression." (PMID 36552722, 2022). "In the MCF10DCIS.com breast cancer cells, the Gemini vitamin D analog BXL0124 blocked Notch-1 activation and the expression of Jagged-1, -2, and DLL-1." (PMID 35408894, 2022). "These genes were also enriched in the PI3K/Akt, Notch1/Hes1 or Akt1/mTOR signaling pathways and were reported to be correlated with LNM in breast cancer." (PMID 36644636, 2022). "Downregulation of the Wnt signaling pathway, cancer stem cell markers oct4, Notch1, EpCAM, and CD44 was a common mechanism encountered in many tested breast cancer cell lines with eugenol." (PMID 36362950, 2022). "Specifically, PYK2 ablation inhibits Notch1 signaling and consequently reduces CCL2 secretion by breast cancer cells, and concurrently reduces the levels of CCR2, CXCR4, IL‐4Rα, and Stat6 activation in macrophages." (PMID 35092356, 2022). "NCSTN is significantly upregulated in breast cancer and induces epithelial-mesenchymal transition (EMT) through Notch1 cleavage." (PMID 36439123, 2022). "Coordinated Notch1 and Ras/MAPK hyperactivation in breast cancer patient specimens was found to be related to poor general survival which led to the identification of cooperation between Notch and Ras/MAPK pathways." (PMID 36017236, 2022). "Disrupting the interaction between DLL4 and Notch1 induces tumor cell apoptosis and inhibits cell proliferation and EMT in breast cancer." (PMID 35844785, 2022). "Notch receptors (NOTCH-1, NOTCH-2, and NOTCH-3) are highly expressed in basal/claudin-low breast cancer subtypes." (PMID 36476410, 2022). "Overexpression of the NOTCH1 intracellular domain with the MMTV promoter [MMTV-Notch1 (intra)] impairs mammary gland development and induces mammary tumors, suggesting the oncogenic role of NOTCH1." (PMID 35846378, 2022). "A large number of factors were discovered that bind within 10,000 bases of the ACBD3 transcription start site across all tissues, and some of these stand out as having roles in breast cancers, including NOTCH1-NICD, CDK9, CTCF, and CEBPB." (PMID 36012147, 2022).
breast cancer (continued). "Upregulation of NOTCH1 and NOTCH3 (perhaps) in basal- like breast cancer cell(BLBCC) leads to secretion of cytokines, such as IL1β and CCL2, which recruit monocytes that mature into tumor-associated macrophages (TAMs) in stroma." (PMID 36517618, 2022). "In accordance with this, NOTCH1 and NOTCH4 were found to be expressed in a subset of breast cancer cells where their expression also correlated with poor prognostic factors." (PMID 33530306, 2021). "In response to chemotherapeutic agents, DYRK2 facilitates phosphorylation-mediated degradation of neurogenic locus notch homolog protein 1 (NOTCH1), which acts as an antiproliferative mechanism in breast cancer cells." (PMID 33376136, 2021). "AP-2 transcription factors interact with the promoter of both Notch 1 and 3 in P19 embryonal carcinoma cells and with the Notch 2 promoter in MCF-7 breast cancer cells." (PMID 34795288, 2021). "A series of molecules such as hypoxia induced HIF-1α, TGF-β, and NOTCH1 have been reported to promote CSC transdifferentiate to endothelial cells or pericytes in glioblastoma, breast cancer, and renal carcinomas." (PMID 33946480, 2021). "Notch1 signaling has been reported as a downstream effector pathway of SIRT1 to affect disorder progression, such as liver fibrosis, breast cancer, and lung cancer." (PMID 34961513, 2021). "It has been reported that Notch1 inhibitors alter the cancer stem cell (CSC) phenotype and reduce the formation of brain metastasis from breast cancer." (PMID 33467780, 2021). "We show that repression of PTEN occurs through the combined action of NOTCH (NOTCH1 or NOTCH2) and EZH2 alterations in a subset of breast cancers." (PMID 33750924, 2021). "In breast cancer, EZH2 increases NOTCH1 expression by directly binding to the NOTCH1 promoter and further promotes CSC properties or expands CSCs17." (PMID 33966039, 2021). "The NOTCH family genes, including NOTCH1, NOTCH2, NOTCH3, and NOTCH4, are highly expressed in breast cancer patients." (PMID 33324444, 2020). "In breast cancer cells, highly active ALDH leads to breast cancer stem cell characterization by upregulating Notch-1 and epithelial-mesenchymal markers." (PMID 33344242, 2020). "A recent study has suggested that Notch 1 suppression of PTEN enhances cell proliferation and stem cell survival in treatment-resistant HER2+ breast cancer, via upregulation of ERK1/2." (PMID 32575680, 2020). "Similar results were demonstrated in vivo, where Notch 1 activation was responsible for tumour dormancy, which led to treatment resistance and drastically faster recurrence of HER2/neu-induced mammary tumours." (PMID 32575680, 2020). "In tamoxifen-resistant ER+ breast cancer patients, Notch 1 and oestrogen receptor-1 (ESR1) showed reciprocal regulation as well as Notch 1 overexpression; potentially indicating Notch 1′s involvement in endocrine resistance." (PMID 32575680, 2020). "Plenty of miRNA-mRNA axes, such as miR-34a-Notch1 axis, miR-125b-Sema4c axis, miR-181-Bcl-2 axis, and miR-27b/CBLB/GRB2 axis, were reported that regulated taxanes-resistance in breast cancer." (PMID 32974144, 2020). "High expression of SNHG7 accelerates breast cancer tumorigenesis and progression by sponging miR-34a to activate EMT and Notch-1 pathway." (PMID 33330080, 2020). "Suppression of Notch1 activity can decrease cell proliferation, migration and invasion by attenuating PI3K/AKT/NF-κB signaling in breast cancer cells." (PMID 31057403, 2019). "This association was evidenced by the results indicating that knockdown of Notch1 and Akt1 abrogates Nanog-mediated radioresistance and Nanog-mediated high ALDH activity in breast cancer cell lines." (PMID 30845764, 2019).
breast cancer (continued). "Ectopic upregulation of miR-34a expression led to partial MDR reversal, reduction of target genes Ccnd1, Notch1 and BCL2 expression and increased apoptotic rates in MDR breast cancer cells." (PMID 35582270, 2019). "Suppression of Notch1 signaling can decrease cell proliferation, migration and invasion by reducing AKT activity in breast cancer cells." (PMID 31057403, 2019). "Several reports have described the therapeutic potency of knocking down Notch-1, STAT3, and β-catenin proteins in breast cancer using siRNA." (PMID 31357721, 2019). "In the current study, we describe a therapeutic potential of single and combinations of siRNA designed for silencing Notch-1, Wnt/β-catenin, and STAT3 in MCF7_DoxS (wild type) and MCF7_DoxR (doxorubicin resistant) breast cancer cells." (PMID 31357721, 2019). "In this study, we developed a doxorubicin resistant MCF7 breast cancer cell line, followed by study of the expression status of important oncogenes including STAT3, β-catenin, and Notch-1." (PMID 31357721, 2019). "In both cases, untransfected breast cancer cells treated with a combination of CDDP with VPA and CDDP with SAHA were much more sensitive than cells with altered Notch1 activity." (PMID 31357442, 2019). "By targeting NOTCH 1 and protein kinase D1 (PRKD1), miR-34a modulates chemosensitivity of breast cancer cells to adriamycin, and stimulates breast cancer stemness and drug resistance, respectively." (PMID 31554373, 2019). "Nrf2‐dependent G6PD/HIF‐1α activation provokes Notch1 signalling by up‐regulation of Jagged1 and Hes1, thereby promoting EMT in breast cancer cells." (PMID 30809937, 2019). "The results show high expression of Notch1 and Jagged1 in Nrf2 overexpression in MCF‐7 and MDA‐MB‐231 breast cancer cells; while Nrf2 knockdown in MCF‐7 and MDA‐MB‐231 cells had the opposite effect." (PMID 30809937, 2019). "Next, we investigated the expression status of the Notch-1, β-catenin, STAT3, CD44, and CD24 markers in doxorubicin resistantMCF7 breast cancer cells (MCF7_DoxR) compared to MCF7 parental cells (MCF7_DoxS)." (PMID 31357721, 2019). "Studies in breast cancer, particularly in the TNBC subtype, demonstrated that the activation of Notch1 promoted stemness, drug resistance, invasion and migration." (PMID 31105691, 2019). "Activation of Notch-1 enhances cell metastasis by promoting EMT in lung cancer, squamous cell carcinoma and breast cancer." (PMID 31057403, 2019). "Notch1 inhibition increased chemotherapy efficacy in TNBC BCSCs (CD44+/CD24−/low population) in vitro and in a patient-derived xenograft breast cancer model." (PMID 30515368, 2018). "We and others have shown that IKKα physically interacts with Notch1 and functions downstream of Notch1 in cervical cancer, T-ALL, ER+ breast cancer and colorectal cancer." (PMID 30564555, 2018). "Importantly, these findings may be translatable to human disease, as analysis of a published database available in Oncomine showed that expression of CCR7 and Notch1 are significantly correlated in primary human breast cancers, particularly in higher grade tumors." (PMID 28137279, 2017). "The study also evaluated the influence of the ADAM10, NOTCH1, NOTCH3, HES1, LFNG and PSEN1 genes on breast cancer recurrence." (PMID 27888801, 2017). "Western blot analyses showed that Notch1 and Notch3 as well as all three Pim family kinases are expressed in MCF-7 breast cancer cells, whereas PC-3 prostate cancer cells express all but Notch3." (PMID 27281612, 2016). "These analyses revealed positive Pearson correlations between PIM1 and NOTCH1 in both types of cancer as well as between PIM1 and NOTCH3 in breast cancer." (PMID 27281612, 2016).
breast cancer (continued). "Previous studies have also reported on the correlation between Notch1 and CD133 in other types of cancers such as glioma, breast cancer, lung cancer and prostate cancer." (PMID 27489358, 2016). "To investigate further the autophagic regulation of Notch1 signaling, we generated a stable Beclin1 knockdown MDA-MB-231 breast cancer cell line." (PMID 27806347, 2016). "In the current study, our data showed that inhibition of Notch1 reversed the EMT process both in vitro and in vivo, and inhibited migration and invasion in breast cancer cells." (PMID 25645291, 2015). "Kaplan–Meier survival analysis of GSE25066, which contained 508 breast cancer patients, demonstrated that RFS rate was lower in patients with high Notch1 expression(p = 0.024)." (PMID 26121683, 2015). "When Notch1 was silenced, both the protein level and mRNA level of Slug were significantly reduced in the Slug-positive MDA-MB-231 human breast cancer cells." (PMID 25645291, 2015). "Notch1 silencing reversed the spontaneous EMT process and inhibited the migration and invasion of breast cancer cells and the growth of xenograft breast cancers." (PMID 25645291, 2015). "It was also reported that miR-34a inhibits proliferation, migration, and invasion of breast cancer cells by targeting several genes including E2F3, CD44, and SIRT1, Notch1 and DLL1." (PMID 25826085, 2015). "Notch1 knockdown increased E-cadherin expression and reversed EMT in vitro and in vivo, and inhibited the motility and invasion capacities of breast cancer cells." (PMID 25645291, 2015). "In summary, the current study demonstrated that overexpression of S100A16 gene promoted EMT via Notch1/ZEB1, ZEB2/EMT pathway in breast cancer cells." (PMID 25287362, 2014). "The analysis of univariate association of categorized and continuous A_HSCOREs of NILCO and targets showed that Notch1 and JAG1 expression were significantly higher in breast cancers positive for Ki67 (p=0.01 and p=0.004 respectively)." (PMID 24716804, 2014). "In the present study, we observed visfatin-dependent regulation of Notch1 gene expression in MDA-MB-231 cells, which affected breast cancer cell growth in vitro and in vivo." (PMID 24970818, 2014). "Notch1 and Notch4 expression were lower, but VEGFR2 expression was higher in stromas from TNBC compared with ER- and ER+ breast cancer stromas." (PMID 24716804, 2014). "Specifically, the investigators elucidated crosstalk between the Notch and PI3K pathway in several different cancer cell lines, including a chemoresistant breast cancer cell line (MCF7), with increased Notch-1 expression and signaling." (PMID 25566499, 2014). "Indeed, among Notch targets several are also Pin1 substrates (e.g. cyclin D1, NF-κB, Survivin), suggesting that in addition to its role in sustaining Notch1 protein levels, Pin1 could promote breast cancer aggressiveness also by enhancing the activity of some Notch-induced Pin1 targets." (PMID 24357640, 2014). "For example, Notch1 inhibition alters CD44+/CD24− population and reduces the formation of brain metastases from breast cancer." (PMID 23651443, 2013). "NOTCH1 activation attenuates E-CADHERIN expression and favors the motility and invasive ability of epithelial human breast cancer MCF-7 cells in vitro." (PMID 23826634, 2013). "We also examined NOTCH1 and NOTCH4 expression because of their role in mouse breast cancer malignancy and their overexpression in triple-negative breast cancer subtypes." (PMID 23826634, 2013). "Notch1 inhibition alters the CD44+/CD24− population and reduces the formation of brain metastases from breast cancer." (PMID 23651443, 2013). "ALDH1A1-negative breast cancer tissue displayed strong NOTCH1 staining (1.92 ± 0.37), compared to ALDH1A1-positive breast cancer tissue (0.61 ± 0.11, P = 0.002)." (PMID 23767668, 2013).